CXCR2 (C-X-C motif chemokine receptor 2)
Diseases named in the same sentence as CXCR2 in open-access papers (continued):
Sharing a sentence is not in itself a finding about the gene and the disease.
pancreatic cancer (continued). "Then, activation of CXCR2 by CXCL1 causes the proliferation of the transformed cell and thus further development of pancreatic cancer." (PMID 37408240, 2023). "Consistent with our observations, a previous study also found a strong downregulation of CXCR2 in neutrophils infiltrated in pancreas cancer tissues." (PMID 36921037, 2023). "In a pre-clinical model of pancreatic cancer, CXCR2 inhibition with pepducin depleted neutrophil and MDSC liver recruitment, suppressed metastases, and increased susceptibility to anti-PD1 therapy." (PMID 35954395, 2022). "CXCR2+ TANs promote tumor-related neutrophil recruitment to the interstitial microenvironment of pancreatic cancer and induce chemotherapy resistance." (PMID 35493517, 2022). "In murine oral, renal, and pancreatic tumor models, CXCR2 inhibition results in neutrophil depletion coinciding with increased survival, T cell infiltration, and immunotherapy response." (PMID 35522219, 2022). "Reducing CXCR2 significantly inhibited the number of TANs in pancreatic cancer, leading to spontaneous, T-cell-dependent tumor growth inhibition." (PMID 36324574, 2022). "Suppressing IL-8 or blocking the IL-8/CXCR2 axis with IFN-γ can enhance the anti-PD-1 efficacy in pancreatic cancer." (PMID 36185222, 2022). "In concordance with our findings, a recent study showed that CXCR2 inhibition was found to augment programed cell death 1 (PD-1) inhibition in pancreatic cancer." (PMID 35517812, 2022). "In vivo, blocking CXCR2 inhibits neutrophil mobilization, and the combination of CCR inhibitors and CXCR2 inhibitors enhances the pancreatic cancer response to FOLFIRINOX chemotherapy." (PMID 36324574, 2022). "Blocking the paracrine activation of CXCR2 leads to attenuation of pancreatic tumor development, reduction of tumor angiogenesis, and prolongation of survival in Ptf1a-Cre; lox-stop-lox-KrasG12D/+; Tgfbr2lox/lox mice." (PMID 35159011, 2022). "Carboxypeptidase E-∆N promotes proliferation and invasion via the upregulation of CXCR2 expression in pancreatic cancer." (PMID 35686102, 2022). "SB225002, a selective CXCR2 antagonist, and SCH-527123, a CXCR1/CXCR2 antagonist, attenuated the effects of conditioned media of senescent hPSCs on the proliferation and migration of pancreatic cancer cells." (PMID 36012531, 2022). "Ala Litman and coworkers explained the importance of the CXCL8-CXCR2 axis in pancreatic cancer, which indicate that the serum chemokine CXCL8 is a better diagnostic and predictive marker than CXCR2, C-reactive protein, classic CA 19-9, and CEA protein." (PMID 35468838, 2022). "These CXCLs, which act on the common receptor CXCR2, are members of the inflammatory chemokine family, and they have similar structures and play important roles in various malignancies, including pancreatic cancer." (PMID 36012531, 2022). "The findings of Zhang and colleagues suggest that the CXCL8-CXCR2 axis can promote trafficking of CXCR2(+) CD68(+) macrophages to pancreatic cancer TME, and the recruitment TAMs can inhibit the efficacy of PD1 blockade." (PMID 35372515, 2022). "The role of CXCR2 ligands/CXCR2 biological axis in pancreatic cancer has been studied in a clinical trial (NCT00851955, results are pending)." (PMID 34290984, 2021). "CXCL1/2/3/5/6/7/8 (receptors are CXCR2) have been demonstrated to be a promoter in tumor angiogenesis within a number of cancer types, including pancreatic cancer, melanoma, and prostate cancer." (PMID 34497764, 2021). "These inhibitors can inhibit pancreatic tumour growth by reducing signaling from CXCR2, which prevents tumour cell proliferation and tumour invasion." (PMID 34452553, 2021). "In pancreatic cancer receptors, CM has the best activity value as an inhibitor of the formation of the CXCR2-NHERF1-PLCβ3 complex in pancreatic cancer cells." (PMID 34452553, 2021).
pancreatic cancer (continued). "More importantly, genetic or pharmaceutical blockade of CXCR2 reduces tumorigenesis and angiogenesis in mice with oesophageal cancer, lung cancer, breast cancer and pancreatic cancer." (PMID 34124076, 2021). "The formation of the macromolecular complex of CXCR2-NHERF1-PLCβ3 in pancreatic cancer cells regulates the signalling activity of CXCR2 and plays an essential role in tumour proliferation and invasion." (PMID 34452553, 2021). "Inhibition of CXCR2 is also tested in patients with pancreatic cancers (clinicaltrials.gov identifier NCT00851955) and metastatic melanoma (clinicaltrials.gov identifier NCT01740557)." (PMID 34359674, 2021). "CXCR2 signalling promotes the progression of pancreatic cancer, where its increased expression correlates with the aggressive stage in the patient." (PMID 34452553, 2021). "In a pancreatic cancer mouse model, deletion or inhibition of CXCR2 enhances infiltration of T cells and extends survival time of mice that are treated with checkpoint inhibitors." (PMID 34359674, 2021). "Overexpressed CXCL8 in pancreatic cancer mediates CXCR2+CD68+ macrophage trafficking to the TME and contributes to cancer progression and PD-1 blockade resistance." (PMID 35011369, 2021). "As a result, CXCR2-expressing CAR T cells provoke greater anti-tumor activity toward recognized αvβ6-expressing pancreatic tumor xenografts." (PMID 33494834, 2021). "Recent studies suggest that CXCR2 plays a crucial role in invasion, angiogenesis, and metastases of various cancer types such as prostate, lung, colon, oral, and pancreatic cancers." (PMID 31999765, 2020). "For example, the C-X-C motif chemokine receptor 2 (CXCR-2) molecule was therapeutically targeted as a mode to overcome the immunosuppressive nature of pancreatic cancer." (PMID 30941175, 2019). "This demonstrates that, similar to IL-8 induced myotube atrophy, myotube atrophy in response to human pancreatic cancer cell CM is mediated through CXCR2." (PMID 31769424, 2019). "The role of CXCR2 in cancer-related MDSCs expansion has been already described in preclinical models, which showed that CXCR2 signaling in the Ly6G+ MDSCs promotes pancreatic tumorigenesis and is required for pancreatic cancer metastasis." (PMID 31395859, 2019). "In tumors, CXCR-2 is overexpressed on immune cells found in the tumor microenvironment of pancreatic cancer." (PMID 30941175, 2019). "Following these promising preclinical results, a phase II clinical trial with the CXCR2 inhibitor AZD5069 is ongoing in pancreatic cancer patients (NCT02583477)." (PMID 30894861, 2019). "CXCL1 binds to the CXCR2, which expresses on HSCs and neutrophils, and several types of cancer including melanoma, lung and pancreatic cancers." (PMID 29642635, 2018). "For instance, CXCR2 blockade improved the response to checkpoint blockade in transplantable rhabdomyosarcoma and spontaneous pancreatic cancer models." (PMID 30355585, 2018). "Ccr5 and Cxcr2 promote pancreatic cancer progression and metastasis (in the case of Cxcr2), and their chemical inhibition has been proposed as cancer immunotherapy." (PMID 30504844, 2018). "Recently, CXCR1 and CXCR2 antagonist are used to treat human melanoma, lung, breast, and pancreatic cancer growth by inhibiting tumor cell proliferation and suppression of angiogenesis and metastasis." (PMID 28484461, 2017). "In this regard, CXCR2 signaling has been shown to regulate KRAS-induced pancreatic cancer growth, whereas IL-8 serves as an autocrine growth factor for malignant mesothelioma maintenance." (PMID 28380429, 2017). "Several research groups reported that CXCL1 and CXCR2 were poor prognostic factors in studies using human samples of several types of cancers including gastric cancer, colorectal cancer, and pancreatic cancer." (PMID 28575019, 2017). "IL-8 and its receptor CXCR2 are significantly upregulated in the tumors and tumor microenvironment in many cancers including colorectal and pancreatic cancers." (PMID 27058419, 2016).
pancreatic cancer (continued). "For example, CXCL1 and CXCL5, secreted by pancreas cancer cells, can activate CXCR2 in fibroblasts to stimulate the production of connective tissue growth factor that, in turn, fuels tumor progression." (PMID 26327350, 2015). "CXCR2 in particular was required for EPC mobilization during pancreatic tumor growth, indicating a critical role for CXCR2 in the regulation of BM-derived progenitor cells with respect to tumor angiogenesis." (PMID 23531764, 2013). "Furthermore, senescence-induced pancreatic stellate cells secrete CXCL1, CXCL2, and CXCL3, and blockade of the CXCR2 axis suppresses pancreatic cancer cell proliferation." (PMID 41155662, 2025). "Also, in pancreatic cancer mouse models, CXCR2+CD68+ macrophages (M2 phenotype) are recruited to the TME by tumor-derived CXCL8, where they contribute to local immunosuppression, thereby reducing the effectiveness of PD-1 blockade therapy." (PMID 38835055, 2024). "Studies in mice suggest that blocking neutrophil recruitment to tumors by inhibition of neutrophil chemokine receptor CXCR2 could be a potential immunotherapy for pancreatic cancer." (PMID 38898176, 2024). "Upon comparison, via flow cytometry, of peripheral blood NK cells in healthy donors and patients with pancreatic cancer, NK cells from pancreatic cancer patients had a downregulated CXCR2 cell surface expression, suggesting that CXCR2 possibly dictates NK cell localization in tumors." (PMID 38339310, 2024). "Therefore, CXC chemokine/CXCR2 signaling is an important mechanism for the occurrence and development of many malignant tumors including pancreatic cancer." (PMID 37576896, 2023). "Furthermore, neutralizing antibody-targeting CXCR2 prevented pancreatic cancer tumorigenesis through inhibiting angiogenesis." (PMID 36612163, 2022). "CXCR2 signaling has been shown to be an excellent therapeutic target for pancreatic cancer." (PMID 36185222, 2022). "CXCL5, a ligand of CXCR2, induces angiogenesis in pancreatic cancer." (PMID 36324574, 2022). "CXCLs/CXCR2 axes stimulate tumor-stromal communication, leading to pancreatic cancer promotion." (PMID 36612163, 2022). "Furthermore, we identified CXCL1, CXCL2, and CXCL3 as SASP factors secreted by senescence-induced hPSCs, and the inhibition of the CXCLs/CXCR2 axis attenuated their stimulating effects on the proliferation and migration of pancreatic cancer cells." (PMID 36012531, 2022). "In addition, TANs inhibit the activity of immune T cells in pancreatic cancer through the CXCR2/CXCL5 signal axis, thus forming an immunosuppressive microenvironment and promoting cancer progression." (PMID 35493517, 2022). "As expected, while tumour conditioned media generated from gemcitabine-treated human and mouse pancreatic cancer cells significantly increased neutrophil migration in vitro, compared with control conditioned media, the presence of the CXCR2 inhibitor SB225002 inhibited neutrophil migration." (PMID 35022267, 2022). "In addition, CXCR2-expressing CAR-T cells were more sensitive to the IL-8-rich microenvironment in pancreatic cancer and had stronger anti-tumor activity against αvβ6-expressing pancreatic tumor xenografts." (PMID 36230724, 2022). "In pancreatic cancer patients, the CXCR2 signaling is also overactivated." (PMID 34359674, 2021). "CXCR2 significantly promotes angiogenesis, proliferation, and invasion of pancreatic cancer." (PMID 35011369, 2021). "Indeed, treatment of pancreatic-tumour-bearing KPC mice with CXCR2 inhibitors and anti-PD-1 antibodies extends survival beyond monotherapy controls." (PMID 33262520, 2021). "Moreover, expression of the receptor for CXCL5, C-X-C-motif chemokine receptor-2 (CXCR2), was upregulated in pancreatic cancer cells." (PMID 31999765, 2020). "Given the immunosuppressive nature of the pancreatic cancer tumor microenvironment and the role played by CXCR-2, inhibiting this molecule could have important implications for immunotherapy." (PMID 30941175, 2019).
pancreatic cancer (continued). "Besides pancreatic cancer, CXCR2 promotes tumorigenesis and metastasis in lung, breast, colon, and skin cancers." (PMID 31731578, 2019). "Furthermore, an increased level of CXCL5 chemokines not only promotes metastasis but is also related to worse prognosis, while CXCR2 inhibitors regress pancreatic tumor development in mice model." (PMID 29662489, 2018). "Moreover, CXCR1 and CXCR2 antagonist are also used to treat human melanoma, lung, breast, and pancreatic cancer growth by inhibiting tumor cell proliferation and suppression of angiogenesis and metastasis." (PMID 28484461, 2017). "Nonetheless, the contribution of GRO-α and its receptor CXCR2 to clinical features and survival of patients with pancreatic cancer remains obscure, and further studies are required for precise evaluation of the therapeutic and prognostic values of GRO-α and CXCR2 in pancreatic carcinoma." (PMID 27472713, 2016). "Antibody-based inhibition of CXCR2 in pancreatic cancer models has previously been shown to block angiogenesis with an accompanying reduction in tumour growth, and a recent study of CXCR2 and oral cancer showed antagonist inhibition of CXCR2 to decrease tumour cell viability." (PMID 24395654, 2014). "For example, the proposed link between low EPCAM expression and the absence of lymph node metastasis in HCC, and the suggestion that CXCR2-mediated ligand competition underlies the hypovascularity of pancreatic cancer, are intriguing, but not directly demonstrated by the present data." (PMID 41228323, 2025). "Although CXCR2 inhibition was shown to reduce neutrophil recruitment to tumor in mice and in in vitro models of human lung cancer and breast cancer, it is unknown whether CXCR2 inhibition could also reduce neutrophil recruitment to human pancreatic tumor tissue." (PMID 38898176, 2024). "Therefore, destroying this CXCR2 complex may become an effective treatment strategy for pancreatic cancer." (PMID 37576896, 2023). "Similarly, the CXCR2-dependent recruitment of neutrophil granulocytes to the stroma of pancreatic cancer where they elicit high immunosuppressive activity and drive disease progression could potentially be targeted by TRPC6 blockers." (PMID 31950205, 2020). "Thus, CPE-ΔN may play an important role in promoting pancreatic cancer growth and malignancy through upregulating the expression of the metastasis-related gene, CXCR2." (PMID 31731578, 2019). "Similarly, disruption of neutrophil recruitment through CXCR2 blockade prevented metastasis formation in cell line, xenograft and spontaneous models of rhabdomyosarcoma, colon and pancreatic cancer, and several CXCR2 inhibitors are currently under clinical investigation." (PMID 30355585, 2018). "However, there was no clear evidence that CXCR2 was associated with the prognosis of pancreatic cancer patients." (PMID 29312644, 2017). "Overall, CXCR2-driven neutrophil activity promotes an immunosuppressive TME and contributes to pancreatic cancer progression." (PMID 41228334, 2025). "Since MDSCs are significant contributors to the immunosuppressive PDAC TME and CXCR2 is important for their recruitment to the PDAC TME, CXCR2 is an attractive target for pancreatic cancer." (PMID 40427538, 2025). "In tumor xenograft models, using human pancreatic cancer cell lines, CXCL8 expression was correlated with a preferential expansion of CXCR2+CD68+ macrophages, which significantly led to the decreased efficacy of anti-PD1 therapy." (PMID 38339310, 2024). "Interruption of PDZ-mediated interaction can eliminate CXCR2 and PLC-β3 signals, thus inhibiting the proliferation of PANC-1 cells (human pancreatic cancer cells)." (PMID 37576896, 2023). "Dual targeting of CCR2 and CXCR2 improves antitumor immunity and FOLFIRINOX response in pancreatic cancer compared with either strategy alone." (PMID 37173915, 2023).
pancreatic cancer (continued). "Studies have confirmed that the decomposition of CXCR2-NHERF1-PLC-β3 macromolecules in vitro and in vivo can inhibit the growth and metastasis of pancreatic tumors." (PMID 37576896, 2023). "Thus, cellular senescence may play a role in the CXCLs/CXCR2 axis in pancreatic cancer." (PMID 36012531, 2022). "Studies verified that CXCR2-expressing CAR T cells transfer more powerfully toward IL-8 and IL-8 containing microenvironment in pancreatic cancers." (PMID 33494834, 2021). "In a PD1-mAb-resistant mouse model of pancreatic cancer, pharmacological inhibition of CXCR2 synergized with anti-PD1 therapy to significantly extend survival, while genetic deletion or inhibition of CXCR2 increased T-cell infiltration into the TME." (PMID 34944914, 2021). "For instance, CXCR2 and CXCL8 are overexpressed in various human cancers, such as oesophageal cancer, pancreatic cancer and ovarian cancer, and this overexpression positively correlates with aggressive tumor behavior and poor prognosis." (PMID 34124076, 2021). "In mouse xenograft models of ovarian and pancreatic cancer, administration of CAR T cells engineered to co-express αvβ6 integrin and CXCR2 significantly reduced tumor growth." (PMID 34944914, 2021). "Loss or inhibition of CXCR2 can improve T cell entry, and combined inhibition of CXCR2 and PD1 in mice with confirmed disease can significantly prolong survival and inhibit pancreatic tumorigenesis and pancreatic cancer metastasis." (PMID 33546693, 2021). "Since neutrophils express C-X-C chemokine receptor–type 2 (CXCR2), they are attracted by ligands like CXCL1/IL-8, CXCL2, and CXCL5, released in pancreatitis and pancreatic cancer." (PMID 33841132, 2020). "This study reveals that CXCR2-mediated neutrophil infiltration and NET formation escalate with pancreatic cancer progression, are enhanced by gemcitabine chemotherapy, contribute to an immunosuppressive microenvironment, and are linked to reduced patient survival." (PMID 41228334, 2025). "For instance, CCR2/CCR5 inhibitors, such as PF-04136309 in pancreatic cancer, could disrupt TAM/Treg recruitment in ESCA, while CXCL8/CXCR2 blockade, trialed in CRC, may reduce MDSC/NET-mediated immunosuppression." (PMID 40134607, 2025). "CXCR2 and its ligands, such as CXCL5, are crucial for TAN recruitment in pancreatic cancer." (PMID 40443678, 2025). "Additionally, the higher expression of the human homolog of mouse Cxcl5, CXCL6, and other ligands of CXCR2 (CXCL1 and CXCL2) was also identified in human pancreatic cancer cells after adding AMP." (PMID 37867243, 2023). "Some researchers took advantage of tumor-produced IL-8 in order to guide the IL-8 receptor (CXCR1 or CXCR2)-expressing CAR-T cells to infiltrate solid tumors (glioblastoma, hepatocellular carcinoma (HCC), ovarian and pancreatic cancer), and stimulate an antitumor immune response." (PMID 35211124, 2022). "engineered interleukin 8 (IL‐8) receptors CXCR1 or CXCR2 in αvβ6‐targeted CAR T‐cells and demonstrated the superior anti‐tumour activity of these armed CAR‐T cells against established αvβ6‐expressing ovarian or pancreatic tumour xenografts." (PMID 36495108, 2022). "For example, CXCR2-modified GPC3-CART had improved trafficking in a hepatocellular carcinoma model, while a CXCR1/2-modified CD70-CART enhanced CART trafficking and efficacy in murine GBM, ovarian cancer and pancreatic cancer models." (PMID 35273619, 2022). "For instance, genetic ablation of Cxcr2 in a transgenic model pancreatic cancer did not affect primary tumor growth, but inhibited metastasis." (PMID 34070438, 2021).